CHEK2 (checkpoint kinase 2)
Diseases named in the same sentence as CHEK2 in open-access papers (continued):
Sharing a sentence is not in itself a finding about the gene and the disease.
breast cancer (continued). "The prevalence of the CHEK2*1100delC variant among women with and without breast cancer varies among countries." (PMID 18253122, 2008). "In our material the CHEK2 1100delC carriers were markedly younger at diagnosis compared to non-carriers, even though the difference was of borderline significance in the two groups of breast cancer cases and the material small." (PMID 17705858, 2007). "Our results indicate that common variants in the ATM, CHEK2 or ERBB2 genes are not involved in modifying breast cancer survival or the risk of tumour-characteristic-defined breast cancer." (PMID 17132159, 2006). "In summary, our findings demonstrate that the CHEK2 1100delC occurs at a low frequency in Swedish women with double primary breast cancer and colorectal cancer, and thus suggests that development of these two tumor types is not sufficient to recommend mutation analysis of CHEK2." (PMID 16539695, 2006). "Compensation of the 1100delC defect in CHK2 by CHK1, or any other mechanism, might explain the rather low breast cancer risk associated with the CHEK2 variant, compared to that associated with truncating mutations in BRCA1 or BRCA2." (PMID 15700044, 2005). "A significant proportion of sporadic breast cancers also demonstrate a similar loss of expression of CHK2, without carrying the CHEK2 1100delC variant." (PMID 15700044, 2005). "Because some studies suggest that the CHEK2 1100delC variant acts as a breast cancer modifier in non-BRCA1/BRCA2 families only, we considered the subset of women known not to be BRCA1 or BRCA2 germline mutation carriers." (PMID 15535844, 2004). "Although CHEK2 germline variants other than 1100delC have been associated with prostate cancer risk, these have not yet been shown to be enriched in breast cancer cases." (PMID 15535844, 2004). "The CHEK2 variants are rare in the western Washington population and, based on accumulated evidence across studies, are unlikely to be major breast cancer susceptibility genes." (PMID 15535844, 2004). "We found no CHEK2 variants in women with a family history of male breast cancer, but there were only five individuals with such a history in our entire sample." (PMID 15535844, 2004). "An increased frequency of CHEK2*1100delC was found among breast carcinoma families without BRCA1 or BRCA2 mutations, associated with an approximately two-fold increase of breast cancer risk in female carriers." (PMID 14970869, 2004). "Neither found evidence to support a role of sequence variation in CHEK2 in familial breast cancer." (PMID 12454775, 2002). "This study provides further evidence that sequence variation in CHEK2 is associated with an increased risk of breast cancer, and implies that tumorigenesis in association with CHEK2 mutations does not involve loss of the wild type allele." (PMID 12454775, 2002). "Breast cancer (BC) risk is significantly associated with pathogenic variants in at least eight susceptibility genes: BRCA1 (MIM#113705), BRCA2 (MIM#600185), PALB2 (MIM#610355), ATM (MIM#607585), CHEK2 (MIM# 604373), BARD1 (MIM#601593), RAD51C (MIM#602774), and RAD51D (MIM#602954)." (PMID 41230741, 2026). "CHEK2 germline pathogenic variants have generally been associated with a moderate increased risk of breast cancer during life in BRCA1/2 negative patients, although an increased risk for syndromic familial non-medullary thyroid carcinomas has also been suggested." (PMID 40448797, 2025). "Against our expectations based on the results from previous studies, CHEK2 c.1100delC associated ER-positive breast cancer patients had similar recurrent disease-free survival, distant disease-free survival, breast cancer-specific survival and overall survival as compared to non-carriers." (PMID 41314031, 2025). "By means of this approach, we successfully mapped SREs in the breast cancer (BC) susceptibility genes BRCA2 (MIM#600185), including exon 17 with a GC-5′ss, CHEK2 (MIM#604373), and RAD51D (MIM#602954)." (PMID 39518003, 2024).
breast cancer (continued). "While there is evidence for association between variants in ATM or CHEK2 and multiple cancer types, the associations have not been consistently evaluated across all cancer types and, with the exception of breast cancer, the strengths of association are unclear." (PMID 39209703, 2024). "Moreover, estimates of breast cancer risk specifically for CHEK2 I157T and S428F GPVs spanned from none to minimal for these variants, based on risks for invasive versus in situ breast cancers." (PMID 39062660, 2024). "Consequently, females with a CHEK2 I157T GPV do not reach the threshold for high-risk breast cancer screening solely based on the presence of this GPV." (PMID 39062660, 2024). "The BC susceptibility genes involved in breast cancer which cause moderate risk are BRIP1, CHEK2, ATM, RAD51C, and PALB2." (PMID 36873936, 2023). "However, to high breast cancer risk associated with alterations in BRCA1 or BRCA2, both studies confirmed association of germline pathogenic CHEK2 variants with moderate breast cancer risk with odds ratio (OR) 2.5 and a cumulative lifetime breast cancer risk of 25%–30%." (PMID 37449874, 2023). "This study evaluated the effect of age at breast cancer diagnosis and cancer family history on the risk of carrying a PV in breast cancer susceptibility genes routinely included in breast cancer predisposition multi-gene panels, ATM, BRCA1, BRCA2, CHEK2, and PALB2." (PMID 37084156, 2023). "However, several of our premenopausal breast cancer patients carried germline variants of unknown/uncertain significance (VUSs) in eight different breast cancer susceptibility genes, namely BRCA1, BRCA2, CHEK2, RAD51C, RAD51D, ATM, BRIP1, and PMS2." (PMID 36011273, 2022). "Regarding breast cancer, in addition to the known high-penetrance pathogenic variants of BRCA1/2, mutations in other high- or intermediate-penetrance genes can increase the risk of cancer and the most common non-BRCA pathogenic or likely pathogenic variants affect PALB2, ATM, and CHEK2 genes." (PMID 33800556, 2021). "In families where there is a strong family history of breast cancer, non-carriers of the familial CHEK2 variant may still be offered moderate risk surveillance, because of the potential of other co-existing familial variants that have not been identified." (PMID 34771713, 2021). "This study identified putative pathogenic variants in ATM, BRCA1, BRCA2, CHEK2, and PALB2 as the most prominent genes for breast cancer, harboring protein-truncating variants that confer significant disease risks (odds ratio of 2.10 to 10.57) to overall breast cancer risk." (PMID 34439109, 2021). "We set up to test the hypothesis of rs1689711 being a CHEK2:c.1100C risk modifier in larger sample collections, starting with 67 CHEK2 patients, as well as 688 non-carrier breast cancer cases and 246 healthy controls." (PMID 34285278, 2021). "In addition, 19 patients (3.5%) carried P/LPVs in MUTYH, while 9 (1.6%) carried the low-risk allele, CHEK2 p.(Ile157Thr); none of them had previous history of colorectal or breast cancer, respectively." (PMID 33429865, 2021). "In addition, the risk of contralateral breast cancer is more than two times as high in patients with the CHEK2 PV compared to patients without this PV." (PMID 33468213, 2021). "They found that pathogenic CHEK2 variants were the third most frequent germline alterations in both cancers (following BRCA1/BRCA2 variants); however, CHEK2 significantly prevailed in whites over blacks in both breast cancer (2.3% vs. 0.15%) and ovarian cancer (1.3% vs. 0%)." (PMID 33322746, 2020).
breast cancer (continued). "Therefore, this study does not rule out the possibility of other rare or common non-breast cancer phenotypes associated with biallelic inheritance of CHEK2 PVs." (PMID 31993860, 2020). "This suggests that CHEK2 pathogenic variants may be predisposing to the in situ stage of breast cancer with some not progressing to the invasive state." (PMID 31060593, 2019). "By this approach, we identified loss‐of‐function mutations in 6/20 (30%) probands, five of which occurred on BRCA1, CHEK2, and ATM and are esteemed to be risk‐relevant according to our studies, while a novel RAD50 truncating mutation is most likely unrelated to breast cancer." (PMID 29271107, 2018). "Therefore, even when a person tests negative for a known familial CHEK2 mutation previously identified in a blood relative, they are still considered to be at an increased risk to develop breast cancer." (PMID 29659587, 2018). "Cancer family history was also similar among these groups when compared to mutation-negative women, except that CHEK2 mutation carriers had a higher proportion of first-degree relatives with breast cancer (87% in mutation carriers vs. 64% in non-carriers, p = 0.007)." (PMID 28649662, 2017). "Moreover, no increased risk of breast cancer due to I157T CHEK2 gene mutation was observed in Moroccan population." (PMID 28680382, 2017). "Indeed, CHEK2 down-regulation in fibroblasts paracrinaly induced the three major mesenchymal markers N-cadherin, Twist-1 and vimentin, and decreased two major epithelial markers E-cadherin and Epcam in breast cancer cells." (PMID 27484185, 2016). "For patients with a strong family history without a known genetic mutation and patients with other breast cancer risk genes such as CHEK2, PALB2, and CDH1, there is insufficient evidence regarding CBC risk to recommend for or against CPM in these patients, and therefore CPM can be considered." (PMID 27469117, 2016). "Additionally, nuclear COMMD1 was suggested to participate in the cellular response to DNA damage, through its ability to interact with the DNA repair proteins Breast Cancer 1 Early Onset (BRCA1), BRCA1-associated RING domain protein 1 (BARD1) and Checkpoint kinase 2 (Chk2)." (PMID 27788210, 2016). "None of the 134 Moroccan breast cancer patients carried the CHEK2 1100delC mutation." (PMID 25674498, 2015). "Our preliminary genetic analysis are consistent with the reported very low frequency of CHEK2 1100delC mutation in North American populations (compared with Northern Europe), rendering CHEK2 1100delC such as an unlikely to be major breast cancer susceptibility genes." (PMID 25674498, 2015). "Narod's recent review supports the view that testing non-BRCA HBC families for mutations in CHEK2 can provide useful information to evaluate the risk of breast cancer and suggests that the relatively high cost of sequencing makes only the targeted search of frequent mutations cost-effective." (PMID 22114986, 2011). "Increased breast surveillance may be proposed for carriers, but when counseling a family with many breast cancer cases, only some of whom carry the CHEK2 mutation, it is unclear what advice may be given to noncarriers." (PMID 22114986, 2011). "These interactions suggest that CHEK2 may also play a role in breast cancer." (PMID 22114986, 2011). "We aimed to assess whether CHEK2 was subject to DAE in lymphoblastoid cell lines (LCLs) from high-risk breast cancer patients for whom no mutation in BRCA1 or BRCA2 had been identified." (PMID 21569354, 2011). "For the gene-expression analysis here, a multivariate analysis was used to identify CHEK2 1100delC-associated effects that were independent of possible confounding effects, especially the ER status, which is the most important mediator of breast cancer biology and subtypes." (PMID 21542898, 2011).
breast cancer (continued). "To estimate the independent effect of CHEK2 1100delC, we fitted a multivariate linear model on the gene-expression data and included the tumor ER status and histopathologic type as well as patient's family history of breast cancer and rs1800566 genotype as covariates." (PMID 21542898, 2011). "Although the gene products of ATM, CHEK2 and ERBB2 are involved in various aspects of breast cancer development and progression, our results suggest that common variation in these genes does not affect survival, tumour-characteristic-defined risk or the overall risk of breast cancer." (PMID 17132159, 2006). "Mutations in the ataxia-telangiectasia mutated (ATM) and checkpoint kinase 2 (CHEK2) genes and amplification of the v-erb-b2 avian erythroblastic leukemia viral oncogene homolog 2 (ERBB2) gene have been suggested to have an important role in breast cancer aetiology." (PMID 17132159, 2006). "Carriers of haplotype 2 in the CHEK2 gene seemed to have a decreased risk of death from breast cancer (P = 0.038) compared with haplotype 1 carriers, whereas carriers of the rare ERBB2 haplotypes seemed to have an increased risk of death from breast cancer (P = 0.009)." (PMID 17132159, 2006). "The ataxia-telangiectasia mutated (ATM; MIM 607585), checkpoint kinase 2 (CHEK2; MIM 604373) and v-erb-b2 avian erythroblastic leukemia viral oncogene homolog 2 (ERBB2; also named HER2; MIM 164870) genes have been suggested to have an important role in breast cancer aetiology." (PMID 17132159, 2006). "However, in agreement with two other breast cancer studies, we observed no suggestive correlation between the R145W and I175T CHEK2 variants and breast cancer risk." (PMID 15535844, 2004). "Higher CHEK2 and JAK2 expression have been correlated with better survival among patients with rectal adenocarcinoma, lung squamous cell carcinoma, breast cancer, ovarian cancer and several other cancer types." (PMID 40177144, 2025). "Materials and Methods: This retrospective study analyzed 36 breast cancer patients from a Romanian clinic (2020–2024) with complete genetic data for XRCC1 (rs1799782), CHEK2 (rs17879961), and XPD (rs238406)." (PMID 40507526, 2025). "Two patients, one with a CHEK2-PV and one with an ATM-PV, had bilateral breast cancer, rendering the MFRA for breast cancer obsolete." (PMID 40805171, 2025). "For breast cancer, there were 6 genes with a posterior probability > 0.9: BRCA2, BRCA1, PALB2, CHEK2, ATM, and MAP3K1." (PMID 40073867, 2025). "Similar findings have been reported in breast cancer, where genes like RAD51 and CHEK2 contribute to radiation sensitivity." (PMID 40652278, 2025). "Recently, even a patient with breast cancer and concurrent PVs in three cancer-related genes (BRCA1, BRCA2, and CHEK2) has been reported." (PMID 38929805, 2024). "These variables were CHEK2 GPV carrier status, personal history of breast cancer, and family history of breast cancer." (PMID 39062660, 2024). "Consequently, the high carrier frequency has enabled GPV-specific breast cancer risks to be estimated for these specific variants, recognizing that this approach is not possible for most CHEK2 GPVs due to the limited sample size of individuals with specific GPVs." (PMID 39062660, 2024).
breast cancer (continued). "The current panel of genes with strong evidence for use in clinical practice include PALB2, CHEK2, ATM, RAD51C and RAD51D with additional genes such as BARD1 (breast cancer) and BRIP1 (ovarian cancer) continuing to emerge." (PMID 39107016, 2024). "Concerning breast cancer, the 1CM-involved genes are highly overlapped in the alterations derived from the breast cancer network, which uses BRCA1, BRCA2, CHEK2, and ATM as reference genes for the disease." (PMID 39125744, 2024). "The detection rate of validated breast cancer genes beyond BRCA1/2 and CHEK2 from the current study, and the literature, is low at ~2%." (PMID 38609177, 2024). "Naturally upregulated by the induction of estrogen, circPGR aggravates breast cancer progression by suppressing its target, miR-301a-5p, which partially binds to CDK1, CDK6, and checkpoint kinase 2 (CHEK2) mRNA." (PMID 38892280, 2024). "CHEK2 GPV carrier status and family history of breast cancer were also examined as predictors of bilateral prophylactic mastectomy and bilateral prophylactic salpingo-oophorectomy in participants without a personal history of breast cancer." (PMID 39062660, 2024). "One possible explanation is that the impact of PGS313 on OS may be confounded by other genetic risk factors, many of which have yet to be identified; several recent papers have found that PGS313 stratifies breast cancer risk in CHEK2, PALB2, and ATM carriers but not BRCA1/2 carriers." (PMID 38704641, 2024). "Cumulative lifetime penetrance estimates for female breast cancer are taken from the literature review performed by the All Syndromes Known to Man Evaluator28–32: 0.35 (ATM), 0.73 (BRCA1), 0.72 (BRCA2), 0.19 (CHEK2), and 0.38 (PALB2)." (PMID 38760335, 2024). "Concordant results in both functional assays were used to categorize CHEK2 VUS from 12 ENIGMA case–control datasets, including 73,048 female patients with breast cancer and 88,658 ethnicity-matched controls." (PMID 37449874, 2023). "Germline PV of other genes of the HR, especially PALB2, CHEK2, and ATM, were found in 0.5–1.5% of patients with unselected breast cancers, and were obviously more frequent among patients with family breast cancer history." (PMID 35158866, 2022). "The detection rate was 4.35% (n=8) for actionable breast cancer PVs (ATM=2, PALB2=4, CHEK2=1, PTEN=1)." (PMID 33758026, 2022). "From 12,182 abstracts, 15 studies measuring gene penetrance covering 5 putative male breast cancer genes were found: ATM, BRCA1, BRCA2, CHEK2, and PALB2." (PMID 35885460, 2022). "On the other hand, some literature also suggested the checkpoint kinase 2 (CHEK2, Chk2) gene role for developing breast cancer." (PMID 33446123, 2021). "Considering the breast cancer only index cases, there were 33 PALB2 PGVs and 43 CHEK2_c.1100delC PGVs (PALB2: OR = 6.16, 95% CI = 1.98–19.21, P = 0.0003; CHEK2: OR = 4.83, 95% CI = 2.01–11.34, P = 0.0001)." (PMID 34113003, 2021). "In particular, the mutation frequency for ATM is 0.78% and for CHEK2 1.08% in unselected breast cancer patients, whereas the prevalence in unaffected women is 0.41% for ATM and 0.42% for CHEK2." (PMID 33919281, 2021).